DES (desmin)
Diseases named in the same sentence as DES in open-access papers (continued):
Sharing a sentence is not in itself a finding about the gene and the disease.
tumor (continued). "Muscle markers were not performed on the previous biopsy, resulting positive in our specimen (Desmin: strong, diffuse expression; Smooth Muscle Actin: strong staining in 10% of tumor cells)." (PMID 35453940, 2022). "A core biopsy of the abdominal mass showed a tumor consisting of spindle cells that expressed desmin and caldesmon with focal SMA staining." (PMID 34986184, 2022). "All these tumors stained positive for vimentin, whereas in a few cases, tumor cells were positive for desmin and SMA." (PMID 36262943, 2022). "In one tumor (mouse #1729), we detected consistent desmin expression by the tumor cells, while other tumor-bearing pinnae showed specific desmin expression in normal skeletal muscle only." (PMID 35468745, 2022). "Expression of beta-catenin at cell-cell contacts was seen in the tumor with desmin positivity (mouse #1729)." (PMID 35468745, 2022). "Immunophenotypic profile of models differed from the paired clinical tumours as LS-BP-1 and LS-BZ-1 PDXs lost expression of the myogenic markers Actin 14A and desmin, respectively." (PMID 33648535, 2021). "The tumor was composed of epithelioid and spindle areas with extensive necrosis, and immunohistochemistry showed positivity with pancytokeratin, Desmin and MyoD1, which were all noted in an external pathology report." (PMID 34514574, 2021). "Microscopically, numerous histiocytes and foamy cells covered the actual tumor cells that were positive for desmin, MyoD1, and myogenin, suggesting striated skeletal muscle cell differentiation." (PMID 34128847, 2021). "The tumor cells often express myogenic markers (α-smooth muscle actin, desmin, and muscle-specific actin) on IHC." (PMID 34461930, 2021). "Immunohistochemically, the tumor cells exhibited a diffuse positive nuclear staining for MyoD-1, cytoplasmic staining for desmin, and smooth muscle actin (SMA)." (PMID 34067464, 2021). "The tumour cells immunohistochemically displayed expression of smooth muscle actin and some of them additionally demonstrated desmin-antigen-reactivity." (PMID 34452465, 2021). "The tumor displayed a strong activation of genes for mesodermal (Desmin, Myog, Myh1 and Myh3) and endodermal (Afp, Krt20) tissue differentiation." (PMID 33468253, 2021). "Immunohistochemically(IHC) analysis revealed that the tumour cells were positive for Desmin, Vimentin, Myo-D1 and Myogenin." (PMID 34670517, 2021). "In the older tumor-bearing Atg7ΔHep livers the number of desmin-expressing HSCs was still at an elevated level." (PMID 32382012, 2020). "Immunohistochemically, the tumour cells were positive for vimentin, α-smooth muscle actin, and desmin." (PMID 32787426, 2020). "Immunohistochemical analysis can be helpful, and the tumor is often positive for smooth muscle actin, vimentin, and desmin." (PMID 31641928, 2020). "Several epithelial markers were elevated in RE, Keratin 13, Keratin 20, and Gastrokine-1, relative to other groups, while neoplasia markers desmin and vimentin were elevated in BE and EAC compared to control." (PMID 32650561, 2020). "Immunohistochemical staining for tumor cells revealed desmin, α-smooth muscle actin (αSMA), and h-caldesmon were all positive, informing a final diagnosis of PHL." (PMID 32648231, 2020). "Immunohistochemically, the tumor cells are positive for desmin, EMA, and CD99 in about 40%–60% of cases." (PMID 32316685, 2020). "Abundant immunoreactivity (-ir) for the muscle marker desmin was found in T0 and the cultured tumour slices." (PMID 32251338, 2020). "Immunohistochemical staining for tumor cells revealed desmin, α-smooth muscle actin (αSMA), and h-caldesmon to be diffusely positive, while c-kit, S100, CD34, CAM5.2, EMA, CD163, and DOG1 were negative." (PMID 32648231, 2020). "It underscores that INI1 immunostaining is required to allow MRT diagnosis, even in desmin/myogenin‐positive tumor, and should be systematically performed for poorly differentiated RMS in infants." (PMID 32087612, 2020).
tumor (continued). "These in vivo findings of decreased pericyte coverage of the tumor vessels in the REST-KO tumors are supported by our previous in vitro studies showing that REST regulated the expression of the pericyte markers desmin and NG2 in ES cells." (PMID 32486064, 2020). "Immunohistochemistry showed that the tumor cells were immunoreactive for epithelial markers and desmin." (PMID 31103034, 2019). "Desmin immunoreactivity showed a diffuse cytoplasmic pattern for the most part, as well as a paranuclear dot-like pattern in a smaller proportion of the tumor." (PMID 31103034, 2019). "Tumor cells showed a high rate of mitotic activity with a 45% rate of Ki-67 expression, positive reaction for desmin, and SMA in all samples." (PMID 31885968, 2019). "Instead, the increased desmin suggests that tumor stress by ALK TKI treatment leads to hypoxia and subsequent angiogenesis and the recruitment of pericytes that bring about the overall increase of CD31-positive vessels." (PMID 31852910, 2019). "Certain subpopulations of pericytes, such as endosialin (CD248) and desmin-overexpressing pericytes, increase tumor vessel permeability; thus, directly promoting tumor cell intravasation." (PMID 31835465, 2019). "Other antigens commonly used for tumor characterization were S‐100, desmin, vimentin, actin, smooth muscle actin, cytokeratin, and DOG1 (data not shown)." (PMID 31397088, 2019). "Tumor cells were strongly positive for MyoD1, desmin, and myogenin, and weakly positive for actin, CD56, and PGP9.5." (PMID 31870387, 2019). "The most likely explanation is the “shared antigen” between the tumor and cardiac muscle, with muscle-specific antigens (desmin and troponin) detected in the tumor." (PMID 31849640, 2019). "Immunohistochemical analysis revealed that the tumor was positive for vimentin and partly positive for desmin and cytokeratin CAM5.2." (PMID 29380091, 2018). "The tumor had a rhabdomyosarcoma component, identified by the presence of cells with eosinophil-abundant cytoplasm that were positive for desmin." (PMID 29380091, 2018). "Immunostaining and quantitation of histological sections for vascular and pericyte markers, MECA-32 and Desmin, showed a decrease in tumor angiogenesis in Vegfr2Cre/+ and DCKO compared to DFF control mice." (PMID 30283071, 2018). "Most importantly, enhanced proliferation in tumors ectopically expressing STK33 was paralleled by augmented levels of desmin, an observation that suggests a causal relationship between STK33 expression and tumor angiogenesis downstream of HSP90." (PMID 29100402, 2017). "On immunohistochemical examination, the tumor cells were positive for alpha-smooth muscle actin, desmin, CD34 and h-caldesmon." (PMID 28214470, 2017). "In vivo studies showed that IL-15 increased neutrophil infiltration, and the expression of adiponectin, desmin and alpha smooth muscle actin (α-sma) in the tumor tissue." (PMID 28379958, 2017). "HE staining revealed that solid tumor samples were strongly connate to the CAM with outgrowth of the tumor invading avian vasculature, which can also be detected by desmin staining." (PMID 28522871, 2017). "Immunohistochemical analyses showed the tumor stained with vimentin, α-smooth muscle actin, desmin, α1-antitrypsin, and α1-antichymotripsin." (PMID 28144858, 2017). "Immunohistochemical studies showed positive results for vimentin, actin, and desmin in tumor tissue, whereas other markers including pan-cytokeratin, thyroglobulin, and TTF-1 were negative." (PMID 27080750, 2016). "Immunohistochemically, ERMS typically express skeletal muscle markers: Tumor cells usually stain positive for vimentin, desmin, myogenin and myoglobin." (PMID 27357857, 2016).
tumor (continued). "Various immunohistochemical studies have supported the fact that DA tumor cells show variable expression of S-100 protein and desmin." (PMID 26984790, 2016). "Immunohistochemical staining of the tumor reveals high positivity for desmin, vimentin, ER, and PR receptor; however it generally reveals negativity for S-100 protein." (PMID 27274880, 2016). "The second case was diagnosed with the same method as in the specimen; the tumor was negatively stained by keratin, S100, and thyroglobulin, and positively stained by vimentin, desmin, and smooth muscle actin." (PMID 27080750, 2016). "Co-stainings of CD31 and desmin showed that the tumor vessel pericyte coverage was similar in all treatment groups in both tumor models." (PMID 27385210, 2016). "While anti‐Ang‐2 treatment had minimal effects on tumor microvessel densities, coverage with desmin+ pericytes was increased." (PMID 26666269, 2016). "Immunohistochemically, the spindle tumor cells show variable staining for smooth muscle actin, desmin, and ALK." (PMID 26762155, 2016). "Interestingly, the impaired proliferation of tumor cells transduced with shPKM2 was associated with decreased blood vessel formation of both intratumoral and extratumoral origin/vessels as revealed by reduced immunoreactivity of von Willebrand Factor (vWF) and desmin." (PMID 26739387, 2016). "Representative CAM-onplants were stained for the proliferation marker Ki-67 to identify the tumor cells and the smooth muscle cell marker desmin to stain small vessels." (PMID 27769056, 2016). "The tumor cells reacted with immunohistochemical stains for desmin, smooth muscle actin, SMMHC, CD34 (focal), and vimentin." (PMID 27747117, 2016). "By histochemical analysis, the tumor was shown a part of positive for desmin and myoglobin and a part of positive for synaphtophysin and vimentin." (PMID 27250580, 2016). "In most cases, tumor cells showed diffuse and strong positive staining for desmin, which would be suggested a myogenic tumor." (PMID 26208724, 2015). "Additional stains on the debulked tumor tissue revealed focal strong positivity for desmin, SMA, HMB-45, melan A, and S100 and strong diffuse positivity for CD99 (membranous) and BCl-2." (PMID 25977823, 2015). "In our case, tumor cells showed only focal positive staining for desmin, which made it difficult for a correct diagnosis." (PMID 26208724, 2015). "In our case, the tumor showed positivity for desmin and negativity for all the other IHC markers like synaptophysin, chromogranin, S100, calretinin, Inhibin, and pan keratin." (PMID 25685588, 2015). "In aid to differential diagnosis, the immunochemistry is very useful because the tumour cells of AMF express desmin and rarely CD34 and smooth muscle actin." (PMID 26187500, 2015). "Immunohistochemically, the tumor cells in both messes were positive for vimentin and desmin diffusely." (PMID 26178751, 2015). "Pericyte coverage of blood vessels within the tumour, detectable by Desmin staining, was increased in siRND3 tumours." (PMID 26132659, 2015). "Immunohistochemical staining of the tumours showed positive staining for desmin and smooth muscle actin; however, immunohistochemistry was negative for cytokeratin and PSA." (PMID 26640482, 2015). "Apart of tumor growth we also investigated angiogenesis in this model by determining vessel density and staining of desmin-immunoreactive pericytes." (PMID 24809298, 2014). "Immunohistochemical analysis revealed that the spindle-shaped tumor cells were diffusely reactive to α-actin smooth muscle and vimentin, and focally reactive to desmin." (PMID 24959254, 2014). "Immunohistochemistry (IHC) revealed that the tumor cells were positive for desmin, estrogen receptor, progesterone receptor and vimentin; the Ki-67 proliferation index was less than 5%." (PMID 24894537, 2014).
tumor (continued). "Immunohistochemical staining with antibodies against vimentin, inhibin, α-smooth muscle actin and the α-helical rod domain of desmin was performed to confirm the diagnosis of this rare tumor." (PMID 25360170, 2014). "The tumor cells had abundant eosinophilic cytoplasm, and expressed estrogen receptors, progesterone receptors and desmin." (PMID 24894537, 2014). "Staining of LLC tumor sections for pericyte marker NG2 and desmin revealed pericyte coverage deficiency, as previously noted." (PMID 24811731, 2014). "Immunohistochemical analysis of tumor sections with an antibody specific for desmin, a marker of perivascular cells, was used to evaluate the effect of Netrin-4 transfection on the tumor vasculature at the cellular level." (PMID 24472220, 2014). "Immunohistochemically, the tumor cells coexpressed an epithelial marker (cytokeratin), a mesenchymal marker (desmin and vimentin), chromogranin A, and cluster of differentiation (CD) antigens, CD99 and CD56." (PMID 25289084, 2014). "Double Desmin/CD31 immunostaining of tumor sections shows that Netrin-4 overexpression in PC3 cancer cells increases coverage of tumor vasculature." (PMID 24472220, 2014). "To test for tumoral Ad5ROBO4 mediated EC cell type specificity, we co-stained tumor sections with antibodies cognate for pericyte, desmin, PDGFRβ, and NG2, or inflammatory cell, CD45, antigens." (PMID 24376772, 2013). "In component B, the tumor cells were positive for desmin, MyoD1, myogenin, CD56, and CD10 and negative for the other antibodies." (PMID 23533892, 2013). "This cell line was derived from a primary tumor with an embryonal histology and expresses MyoD, myogenin, and desmin (at very low levels)." (PMID 23882450, 2013). "The tumour cells express desmin, neuron specific enolase (NSE), EMA, and vimentin and show a high proliferative activity." (PMID 23406299, 2013). "Antibody staining showed similarities between the cell line and the original tumor, as both stained positive for desmin, vimentin, glycolipid, ganglioside Gq, thy-1 and Gp44; and negative for GFAP, cytokeratin, neurofilament RT97, and myoglobin." (PMID 23882450, 2013). "Immunohistochemically, all tumors expressed CD117, four tumors PDGFRA, ten tumors CD34, eight tumors smooth-muscle actin, one tumor desmin, and S-100 was positive only in the intermixed dendritic cells." (PMID 22350270, 2013). "The tumor specimen was designated RMS based on the presence of desmin intermediate filaments, and assigned embryonal histology." (PMID 23882450, 2013). "While the tumor biopsy was positive for desmin staining, the HX170c cell line was almost completely negative for this marker when cultured in vitro, except when grown to almost complete confluence." (PMID 23882450, 2013). "By light microscopy, tumor cells show immunohistochemical reactivity for epithelial (keratin, epithelial membrane antigen), neural (neuron-specific enolase), and muscle (desmin) markers." (PMID 22550424, 2012). "Desmin-positive, αSMA-negative cells (arrowheads) are correspondingly more abundant in tumor vessels in NG2 null mice." (PMID 22531600, 2012). "While desmin-positive, αSMA-positive pericytes are present in tumor vessels in both wild type and NG2 null mice (arrows), the abundance of these mature cells is reduced two-fold in the absence of NG2." (PMID 22531600, 2012). "The spindle cell component expressed vimentin (Dako), desmin (Invitrogen, Camarillo, CA) in 10% of tumour cells, and myogenin (Dako) in 10% of tumour cells indicating partial rhabdomyosarcoma-like differentiation, EGFR (Invitrogen), and CD56 (Invitrogen)." (PMID 23006472, 2012). "These tumors are heterogeneous and demonstrate variable expressions of smooth muscle actin, muscle-specific actin, and desmin in different parts of the tumor." (PMID 22540324, 2012).
tumor (continued). "Complementary to these in vitro observations, morphine in clinically used doses increased desmin- and PDGFRβ-positive cells in the tumor vasculature of mice, suggestive of increased proliferation and/or recruitment of vessel-associated pericytes." (PMID 22315595, 2012). "Desmin and vimentin double immunostaining was performed on 17 tumor samples to assess co-localisation." (PMID 22141345, 2011). "Taken together, our results show that the desmin expression is derived from both stromal myofibroblasts surrounding malignant crypts and from pericytes found in close contact with the tumor microvessels." (PMID 22141345, 2011). "Tumor over-expression of one such protein, desmin, was quantified using immunofluorescence staining in a larger cohort." (PMID 22141345, 2011). "Using double-immunostaining we found different populations of cells within the tumor stroma i.e. vimentin-positive cells, as well as cells positive for both vimentin and desmin and some cells staining positive for desmin only." (PMID 22141345, 2011). "Next, we determined the impact of the PDGF-BB recombinant protein on MPT through the detection of tumor blood vessel-pericyte markers, such as Desmin and α-SMA." (PMID 20687910, 2010). "Immunohistochemically, the stromal cells of the tumor show strong positivity for vimentin and variable positivity for desmin, α-smooth muscle actin, and CD34." (PMID 21143833, 2010). "Both the elbow emboli with the extratumoral foci of FRMS and the intratesticular tumor were positive for Myogenin, MyoD1, Vimentin and Desmin." (PMID 20701800, 2010). "Immunohistochemically the majority of tumor cells displayed a positive reaction for smooth muscle actin and desmin, confirming smooth muscle differentiation of the tumor." (PMID 21092216, 2010). "Our data suggests that MSC do contribute to the perivascular formation within the admixed Skov-3 tumors because much of the human specific α-SMA and desmin positive staining is evident around tumor vessel structures." (PMID 19352430, 2009). "Histologically, the tumor cells are polygonal with abundant eosinophilic cytoplasm and eccentric nuclei and on immunostaining, these cells are variably positive for desmin, vimentin, GFAP, CK, EMA, SMA and synaptophysin." (PMID 18439235, 2008). "In the present case, the IHC is positive for EMA and desmin, which are smooth muscle markers and CD-68 is an inflammatory marker, suggesting the tumor to be IMT." (PMID 16212671, 2005). "The tumour cells were positive for vimentin and smooth muscle actin, butnegative for desmin, NSE, Factor VIII, chromogranin, cytokeratin." (PMID 18521375, 2003). "The tumor cells uniformly lack the expression of desmin, S-100, and CD34." (PMID 39860616, 2025). "The resected specimen showed that the tumor contained proliferation of spindle-shaped cells and arranged in fascicular pattern, which was immunohistochemically positive for smooth muscle actin and desmin." (PMID 40625542, 2025). "In that study, the marker protein desmin was visualized to detect the tumor cells." (PMID 39869598, 2025). "The resected specimen showed that the tumor contained a proliferation of spindle-shaped cells arranged in a fascicular pattern, which was immunohistochemically positive for desmin, SMA, h-caldesmon, CAM5.2, and EMA (data not shown), and negative for c-kit, AE1/AE3, CD34, and S-100 (data not shown)." (PMID 40625542, 2025). "Immunohistochemistry showed that the tumor cells are positive for desmin and myogenic." (PMID 41061403, 2025).